MAP1LC3C (microtubule associated protein 1 light chain 3 gamma)
Description:
Ubiquitin-like modifier that plays a crucial role in antibacterial autophagy (xenophagy) through the selective binding of CALCOCO2. Recruits all ATG8 family members to infecting bacteria such as S.typhimurium. May also play a role in aggrephagy, the macroautophagic degradation of ubiquitinated and aggregated proteins.
Synonyms: ATG8J; LC3C
Tractability: No criterion of Open Targets' tractability assessment is met for any kind of drug.
Gene: Protein-coding gene on chromosome 1 (241,995,188 to 242,001,584, reverse strand). Ensembl gene ENSG00000197769.
Subcellular location: Cytoplasmic vesicle, autophagosome membrane; Endomembrane system; Cytoplasm, cytoskeleton
Subcellular location (Human Protein Atlas): Cytoplasmic bodies
Pathways (Reactome):
Autophagy: Macroautophagy
Gene Ontology:
Molecular function: phosphatidylethanolamine binding; protein binding; ubiquitin protein ligase binding; phospholipid binding
Biological process: aggrephagy; autophagosome maturation; cellular response to starvation; macroautophagy; autophagosome assembly; cellular response to nitrogen starvation; mitophagy; autophagy; response to stress
Cellular component: autophagosome; cytoplasmic ribonucleoprotein granule; endomembrane system; autophagosome membrane; cytosol; organelle membrane; cytoskeleton
Genetic constraint (gnomAD): Loss-of-function variants: 12 observed, 11.52 expected, observed/expected ratio (o/e) 1.04, 90% interval 0.67 to 1.66. The upper end of that interval is the gene's LOEUF score, 1.66, which puts it in group 6 of 6, group 1 being the genes least tolerant of losing a copy. Missense variants: 177 observed, 196.66 expected, observed/expected ratio (o/e) 0.9, 90% interval 0.8 to 1.02. Synonymous variants: 70 observed, 72.86 expected, observed/expected ratio (o/e) 0.96, 90% interval 0.79 to 1.17.
Homologues: Orthologues: chimpanzee MAP1LC3C (99% identical), macaque MAP1LC3C (95% identical), dog MAP1LC3C (79% identical), pig MAP1LC3C (78% identical), zebrafish map1lc3cl (51% identical), Caenorhabditis elegans lgg-2 (37% identical). Paralogues in human: MAP1LC3A (47% identical), MAP1LC3B (46% identical), MAP1LC3B2 (45% identical), GABARAPL2 (34% identical), GABARAP (31% identical), GABARAPL1 (31% identical).
Diseases named in the same sentence as MAP1LC3C in open-access papers:
MAP1LC3C is named in the same sentence as 28 diseases in open-access papers, as found by Europe PMC text mining. Sharing a sentence is not in itself a finding about the gene and the disease. The quoted sentences say what the papers report.
colon cancer (3 papers, 2020 to 2022). "MAP1LC3C is a marker that indicates poor prognosis in patients with colon cancer, low-grade glioma and lung adenocarcinoma." (PMID 35308199, 2022). "We obtained the risk score of each case with colon cancer; risk score = (0.46121 × expression of ULK3) + (0.650715 × expression of ATG101) + (1.521474 × expression of MAP1LC3C) + (0.641122 × expression of TSC1) + (0.243022 × expression of DAPK1) + (-0.17015 × expression of SERPINA1)." (PMID 34315829, 2021). "We identified 6 prognostic-related ARGs (ULK3, ATG101, MAP1LC3C, TSC1, DAPK1 and SERPINA1) to formulate a novel autophagy-related signature, which could stably predict the survival of patients and indicate the extent of immunosuppressive microenvironment in colon cancer." (PMID 34315829, 2021).
colorectal cancer (3 papers, 2021 to 2022). A primary or metastatic malignant neoplasm that affects the colon or rectum. "MAP1LC3C (microtubule‐associated protein 1 light chain 3 gamma), a critical structural protein in autophagosome membrane, has been reported to be an independent prognostic biomarker in colorectal cancer." (PMID 35611939, 2022). "The expression of ATG4D and MAP1LC3C is low in colorectal cancer, and ATG4D is related to the poor prognosis of pancreatic cancer." (PMID 33604190, 2021). "MAP1LC3C is involved in the KEGG pathway of ferroptosis and was found to be downregulated in colorectal cancer." (PMID 33540700, 2021).
glioma (2 papers, 2022). A benign or malignant brain and spinal cord tumor that arises from glial cells (astrocytes, oligodendrocytes, ependymal cells). "Moreover, MAP1LC3C, which belongs to the same gene family, has significant prognostic and immunotherapeutic value in pan-cancer, especially low-grade gliomas." (PMID 35571123, 2022).
Pancreatic cancer (2 papers, 2016 to 2021). "A markedly high number of copy number deletions were also observed for the PIK3C3 gene in Pancreatic cancer (24%), whereas copy number amplifications for ATG9B (17%), ATG4B (16%) and MAP1LC3C (13%) were commonly found." (PMID 27256984, 2016).
breast carcinoma (1 paper, 2024). "MAP1LC3C has been shown to play a tumor-suppressing role in breast cancer and renal clear cell carcinoma development." (PMID 39726707, 2024).
Hernia (1 paper, 2021). "The microtubule associated protein 1 light chain 3 γ (MAP1LC3C), vitrin (VIT), aggrecan (ACAN), alkaline ceramidase 2 (ACER2), potassium calcium-activated channel subfamily M α 1 (KCNMA1) and synaptopodin 2 (SYNPO2) genes are highlighted as candidates to trigger both types of hernia." (PMID 33513662, 2021).
lung squamous cell carcinoma (1 paper, 2025). "Analysis of the gene expression of the lung squamous cell carcinoma (LUSC) cohort from The Cancer Genome Atlas (TCGA) revealed a significant decrease in MAP1LC3C mRNA expression in tumors." (PMID 39928678, 2025).
meningioma (1 paper, 2024). A generally slow growing tumor attached to the dura mater. "Future experiments may offer a better understanding of the molecular mechanism of MAP1LC3C function in tumor cells and test whether it plays a positive role in meningioma development." (PMID 39726707, 2024). "The most significant DEG in GSTM1 null meningiomas was upregulation of MAP1LC3C, which is located on chr1q43, and is required for the formation of autophagosomal membranes for autophagy-related processes and cell homeostasis, but is not routinely deleted in meningiomas." (PMID 39726707, 2024). "While this model is partially supported by the increases in MAP1LC3C and NEDD4 expression in the GSTM1- meningiomas, future studies will be needed to investigate the various components of this model at both the mRNA and protein level." (PMID 39726707, 2024). "It was observed that meningiomas in this cohort harbored either GSMT1 or MAP1LC3C downregulation only and there were no samples with under expression of both." (PMID 39726707, 2024).
ovarian carcinoma (1 paper, 2022). A malignant neoplasm originating from the surface ovarian epithelium. "The OS of ovarian cancer patients prolonged with the high-expression of ATG7, G6PD, SLC3A2, MAP1LC3C and PTGS2, but shrank with the increased expression of NFS1, VDAC2, ACSL3." (PMID 35039008, 2022).
cancer (15 papers, 2013 to 2025). A tumor composed of atypical neoplastic, often pleomorphic cells that invade other tissues. "We observed that low expression of the autophagy-related protein MAP1LC3C in cancers is associated with decreased CIITA and HLA class II expression and with reduced immune cell infiltration." (PMID 39928678, 2025). "In conclusion, we show that reduced MAP1LC3C associates with cancers that display low infiltration of immune cells (“immune cold tumors”) and controls HLA class II expression through the regulation of CIITA." (PMID 39928678, 2025). "Therefore, MAP1LC3C expression is closely associated with the tumour immune microenvironment in a variety of cancers." (PMID 35308199, 2022). "Given the differential expression of MAP1LC3C in many cancers, GSEA was used to assess the biological function of MAP1LC3C in 33 cancer types." (PMID 35308199, 2022). "Some bioinformatics analyses have revealed the potential value of MAP1LC3C in cancer, but its role and mechanism in GC has seldom been discussed systematically up to now." (PMID 36173625, 2022). "Consistent with previously reported results, differentially expressed MAP1LC3C has certain prognostic values in some cancers, especially COAD, LGG and LUAD." (PMID 35308199, 2022). "Correlation analysis of 23 immune inhibitors showed that MAP1LC3C expression was significantly correlated with various immune inhibitors agents of different cancer types, especially CHOL, LGG and PAAD." (PMID 35308199, 2022). "While the relevance of FH, EXO1, MAP1LC3C and PLD5 functions to the development of cancer is plausible, that of the associated RGS7 is intriguing and deserves comments." (PMID 23555580, 2013). "Analysis of TCGA datasets reveals reduced MAP1LC3C expression in cancer." (PMID 39928678, 2025). "In this study, we show that MAP1LC3C directly determines HLA class II expression in cancer cells." (PMID 39928678, 2025). "Together, our data suggest that reduced MAP1LC3C expression by cancer cells results in immune evasion advantages and may be used as a biomarker to identify immune responsive NSCLC tumors." (PMID 39928678, 2025). "Activity scores were calculated using ssGSEA to assess the MAP1LC3C activity in pan-cancer." (PMID 35308199, 2022). "Notably, KIRP, LGG and UCEC showed significant differences in all four analyses above, and high MAP1LC3C expression suggested a poor prognosis in all three types of cancers." (PMID 35308199, 2022). "The results indicate that MAP1LC3C expression varies in different cancer types." (PMID 35308199, 2022). "In addition, MAP1LC3C activity in 14 cancer types was consistent with changes in transcription levels." (PMID 35308199, 2022). "This study reports that the expression level of MAP1LC3C is related to cancer immunity." (PMID 35308199, 2022). "Therefore, this study aims to elucidate the role of MAP1LC3C in the immune system and its impact on cancer prognosis and immunotherapy, as well as to provide some references for therapeutic agents." (PMID 35308199, 2022). "Therefore, the use of TCGA and GTEx databases for pan-cancer analysis helps to determine the differential expression and role of MAP1LC3C in various types of cancer." (PMID 35308199, 2022). "The genes ITGA3, HSPA8, CTSD, ATG12, CLN3, ATG7, and MAP1LC3C negatively influenced patient survival, whereas WIPI1 may protect the patients from cancer-related death." (PMID 35186475, 2022). "If the transcription levels could not be matched with MAP1LC3C activity in certain cancers, it indicates that it may be due to post-transcriptional protein level modifications or protein metabolism, which affect MAP1LC3C expression." (PMID 35308199, 2022). "MAP1LC3C can mediate the selective autophagy process of METRTK, thereby inhibiting the invasion of cancer cells, and may play an essential role in the distant metastasis of cancer cells." (PMID 34636718, 2021). "Therefore, CXCR4, PDCD1 and MAP1LC3C may function as non-negligible factors in cancer immunity." (PMID 36173625, 2022).
tumor (14 papers, 2013 to 2025). "In addition, MAP1LC3C correlates with tumor-cell associated CD80 and CD86, cell costimulatory surface proteins that are primarily expressed on antigen-presenting cells (APCs) and tumor cells." (PMID 39928678, 2025). "In proportional odds models, the associations with tumor size were marginal and reached the highest statistical significance at rs28627534 (P=0.0021), a common SNP located 3 kb downstream of microtubule-associated protein 1 light chain 3 gamma (MAP1LC3)." (PMID 26113603, 2015). "In tumor cells, MAP1LC3C binds to the ligand-activated oncogenic receptor c-Met for autophagic degradation, thereby mediating a tumor suppressive function." (PMID 39928678, 2025). "This study aimed to comprehensively investigate the differential expression of MAP1LC3C between the normal and tumour tissues and to study the prognostic effect and potential immunotherapeutic value of MAP1LC3C for various tumours." (PMID 35308199, 2022). "Two other genes of potential relevance to tumor growth, MAP1LC3C (microtubule associated protein 1 light chain 3 gamma) and PLD5 (phospholipase D family, member 5) colocalize to chromosome 1q43." (PMID 23555580, 2013). "As a relatively novel member, the function of MAP1LC3C in tumours still need to be investigated." (PMID 35308199, 2022). "Considering that several tumours in the TCGA database do not include normal sample data, normal sample data from the GTEx database were integrated with the tumour sample data from the TCGA database to analyse the expression differences of MAP1LC3C in 33 tumour types." (PMID 35308199, 2022). "TCGA data were used to analyse MAP1LC3C activity in 33 tumour types." (PMID 35308199, 2022). "Conversely, a pervasive decrement was witnessed in the expression of GABARAPL1, MAP1LC3C, VTN, and IL6 in nearly all tumor specimens relative to their paired normal tissue counterparts." (PMID 38460947, 2024). "In both normal and tumor tissue, the highest levels of gene expression were observed for GABARAPL2, followed by MAP1LC3B and MAP1LC3A, the lowest for MAP1LC3C." (PMID 30374741, 2018).
MAP1LC3C also shares sentences with these, for which no sentence is quoted: gastric cancer (2 papers); glioblastoma (2); lung adenocarcinoma (2); renal carcinoma (2); bladder carcinoma (1); colon adenocarcinoma (1); colorectal tumors (1); esophageal carcinoma (1); head and neck squamous cell carcinoma (1); Insulin resistance (1); kidney cancer (1); neuroblastoma (1); neuronal ceroid lipofuscinosis (1); Obesity (1); rectum adenocarcinoma (1); renal clear cell carcinoma (1); stomach adenocarcinoma (1).